NTN1 (netrin 1)
Diseases named in the same sentence as NTN1 in open-access papers (continued):
Sharing a sentence is not in itself a finding about the gene and the disease.
colitis (7 papers, 2012 to 2025). Inflammation of the colon. "For this purpose, the authors used an osmotic pump system to treat mice with recombinant netrin-1 during DSS colitis." (PMID 35910389, 2022). "Recent studies had determined that either administration of recombinant netrin-1 or overexpression in colon epithelial cells suppressed dextran sodium sulfate (DSS) colitis, reduced epithelial cell apoptosis and inflammation." (PMID 24720832, 2014). "Since previous studies had shown a protective role of Adora2b signaling during DSS colitis or intestinal ischemia and reperfusion, subsequent studies addressed the functional role of the Adora2b in netrin-1-elicited gut protection." (PMID 35910389, 2022). "We tested the hypothesis that UNC5B receptor is a critical mediator of protective function of netrin-1 in dextran sodium sulfate (DSS)-induced colitis using mice with partial deletion of UNC5B receptor." (PMID 24720832, 2014). "Similarly, additional investigations in the setting of DSS colitis in mice with partial genetic deficiency of netrin-1, a molecule implicated in the modulation of leukocyte trafficking, indicate a role for A2BR in mediating netrin-1 protective effects." (PMID 39188525, 2024). "However, the receptor that mediates netrin-1 protective activities in the colon during colitis remains unknown." (PMID 24720832, 2014). "Indeed, numerous studies have reported anti-inflammatory actions of netrin-1, such as reducing neutrophil infiltration, attenuating pro-inflammatory cytokine production, and promoting the resolution of inflammation in models of peritonitis, colitis, ischemia–reperfusion injury, and sepsis." (PMID 40728980, 2025). "Netrin-1 also modulates colon-kidney cross talk through reducing both the production and activity of IL-6 as demonstrated in a mouse model of DSS-colitis." (PMID 35250531, 2021). "Although netrin-1 treatment is beneficial in colitis, it does not directly influence permeability of the gut, protected by epithelial cells." (PMID 34576252, 2021). "However, spatial regulation of netrin-1 and its receptors in colitis model are not clearly examined." (PMID 24720832, 2014).
diabetic retinopathy (7 papers, 2019 to 2023). "Netrin-1 mRNA and protein expression were significantly elevated in retinal tissues of diabetic retinopathy (DR) mice." (PMID 37153740, 2023). "These fragments of truncated netrin-1 promote diabetic retinopathy, exacerbate retinal and macular edema." (PMID 35008701, 2021). "Hence, the severity of diabetic retinopathy may cause a delayed netrin-1 response." (PMID 34058994, 2021). "Netrin-1 has been shown to increase the progression of diabetic retinopathy due to its pro-angiogenic effects." (PMID 34058994, 2021). "In contrast, the full netrin-1 protein maintains blood–brain barrier function and mitigates the development of diabetic retinopathy." (PMID 35008701, 2021). "Furthermore, it has been described that proteolytic fragments of Netrin-1, signalling trough UNC5b, can increase the vascular permeability in diabetic retinopathy, a phenomenon that we cannot rule out in our system." (PMID 30897795, 2019).
lung carcinoma (7 papers, 2013 to 2025). "We found a strong netrin-1 upregulation especially in brain metastases of lung carcinomas (NSCLC and SCLC) as compared to normal lung tissue." (PMID 24647424, 2014). "In conclusion, the study report here is the first to unravel Naa10 as the negative regulator of NTN1 and its receptor UNC5B in human lung carcinoma cell lines and caudal half region of E10 mouse embryos." (PMID 27910960, 2016). "Increased serum Netrin-1 is found in gastric and lung cancers and it is reduced after chemotherapy, but the levels do not show correlations with the patient survivals." (PMID 38638604, 2024). "First preclinical studies revealed that the inhibition of netrin-1 interaction with its receptors by a decoy recombinant DCC fragment (DCC-5Fbn) led to increased tumor cell death and significant reduction of the tumor mass in a murine xenograft lung cancer model." (PMID 24647424, 2014).
osteoarthritis (7 papers, 2021 to 2026). A noninflammatory degenerative joint disease occurring chiefly in older persons, characterized by degeneration of the articular cartilage, hypertrophy of bone at the margins and changes in the synovial membrane. "NTN1 promotes axon guidance in neurons and has been implicated in the ingrowth of sensory neurons in in vivo models of experimental disc degeneration and osteoarthritis and may also promote angiogenesis." (PMID 38173036, 2024). "Mice lacking netrin-1 experienced milder OA pain, suggesting that inhibiting netrin-1 or DCC in osteoclasts can alleviate osteoarthritis-related pain." (PMID 40723793, 2025). "In an osteoarthritis (OA) mouse model, we found a role for osteoclast-secreted netrin-1 in the induction of sensory nerve axonal growth in the subchondral bone." (PMID 37961590, 2024). "Aberrant subchondral bone remodeling is a critical factor in pathological changes of osteoarthritis, and sensory innervation induced by netrin-1 from aberrant subchondral bone remodeling is responsible for osteoarthritis pain." (PMID 33646122, 2021). "We have previously shown that Netrin-1, secreted by osteoclasts, acts as a key nerve axon attractant factor, drawing nociceptive sensory innervation to the affected regions as observed in models of osteoarthritis and LBP." (PMID 39257984, 2024).
pancreatic adenocarcinoma (7 papers, 2011 to 2020). "For some cancer subtypes such as adenocarcinomas of the pancreas, it was demonstrated that netrin-1 is either associated with significantly earlier relapse or worse patient overall survival." (PMID 24647424, 2014). "Nonetheless, in a recent study, NTN1 was found strongly up-regulated in pancreatic adenocarcinomas and this aberrant NTN1 overexpression was associated with resistance to apoptosis for both tumor and endothelial cells." (PMID 21789787, 2011). "Tumor cell migration stimulated by NTN1 was seen in melanoma, glioblastoma, and pancreatic adenocarcinomas." (PMID 30923634, 2019). "There is also evidence that netrin-1 enables an increased supply of oxygen and nutrients to tumor cells by the formation of new blood vessels especially in the context of pancreatic adenocarcinomas." (PMID 24647424, 2014). "Netrin-1 acts as an oncogene, and its upregulation was found in several cancers, including metastatic breast cancer, non-small-cell lung cancer, neuroblastomas, and pancreas adenocarcinomas." (PMID 30923634, 2019). "Here, we investigate whether netrin-1 is involved in the in vivo growth of pancreatic adenocarcinoma." (PMID 27034160, 2016). "It was thought that netrin-1 was absent in the normal adult pancreas, but netrin-1 has been found in pancreatic adenocarcinoma and is implicated in tumorigenesis." (PMID 23029434, 2012).
Parkinson disease (7 papers, 2019 to 2025). A progressive degenerative disorder of the central nervous system characterized by loss of dopamine producing neurons in the substantia nigra and the presence of Lewy bodies in the substantia nigra and locus coeruleus. "Seven eQTLs (telomere length) and one eQTL(Parkinson’s disease (motor and cognition)) associated with NTN1 show effects on transcription factor binding." (PMID 32251318, 2020). "However, further investigation is necessary to fully understand the complex mechanism by which Netrin-1 contributes to the pathogenesis of heart failure and Parkinson’s disease." (PMID 41531492, 2025). "NTN1 has been proposed as a potential candidate gene for Parkinson’s disease treatment." (PMID 38534778, 2024). "Gut inflammation induces C/EBPβ activation, which leads to both BDNF and Netrin-1 reduction and triggers non-motor and motor symptoms of Parkinson’s disease." (PMID 35743271, 2022).
endometriosis (6 papers, 2020 to 2025). The growth of functional endometrial tissue in anatomic sites outside the uterine body. "Netrin-1 is thought to mediate endometriosis-associated pain by promoting nerve fibre infiltration in endometriotic lesions." (PMID 40215752, 2025). "The expression levels of Netrin-1 are significantly greater in the serum and endometriotic lesions of women with endometriosis and are positively correlated with the severity of endometriosis-associated pain." (PMID 39894821, 2025). "The tendency toward the M1 polarization of macrophages in endometriosis has been associated with the increased production of netrin-1, a neuronal guidance signaling molecule known to also support neoangiogenesis by enhancing endothelial cell motility and morphogenetic potential." (PMID 39056769, 2024). "Studies indicate that serum levels of netrin-1 are significantly elevated in endometriosis patients and are positively correlated with pain symptoms." (PMID 40723793, 2025). "The local accumulation of netrin-1 produced by macrophages promotes the occurrence and development of endometriosis by regulating the proliferation, tubule formation, migration, and invasion of vascular endothelial cells and inducing neuroangiogenesis." (PMID 40723793, 2025). "A study was shown that in endometriosis macrophage-derived Netrin-1 was vital for neuro-angiogenesis while another shown that Netrin-4 was crucial for maintaining blood vessel by regulating endothelial and perivascular cells." (PMID 33088218, 2020). "In addition, human studies have reported that in patients with endometriosis, netrin-1 and DCC levels are increased in endometrial tissues, and patients with small fiber neuropathy have increased netrin-1 gene expression in keratinocytes." (PMID 35743067, 2022).
myocardial ischemia (6 papers, 2019 to 2025). A disorder of cardiac function caused by insufficient blood flow to the muscle tissue of the heart. "Several previous studies have implicated netrin-1 signaling in attenuating myocardial ischemia and reperfusion injury, and have also identified signaling events related to classic netrin-1 receptors, e.g., via DCC signaling." (PMID 35910389, 2022). "Recent studies from our laboratory had shown that PMN-derived netrin-1 functions to attenuate in situ myocardial ischemia and reperfusion injury." (PMID 36247475, 2022). "Taken together, these studies provide additional support for the concept that myeloid HIF1A provides cardioprotection through transcriptional induction of its target gene netrin-1, leading to attenuated myocardial ischemia and reperfusion injury." (PMID 36247475, 2022). "Together, these studies highlight a functional role of myeloid-dependent HIF1A in attenuating myocardial ischemia and reperfusion, and its transcriptional target netrin-1." (PMID 36247475, 2022). "Other animal studies have shown that Netrin-1 induces angiogenesis, protects against a myocardial ischemia-reperfusion injury, and decreases infarction size by increasing NO." (PMID 32455061, 2020). "Based on these studies, using HIF stabilizers or treatment with recombinant netrin-1 may represent novel approaches to treat or prevent myocardial injury during myocardial ischemia and reperfusion." (PMID 36247475, 2022). "Netrin-1 has been shown to protect against a myocardial ischemia-reperfusion injury and to reduce infarction size by inhibiting apoptosis and increasing myositis function through ERK1/2 inactivation immediately followed by NO production from serine 1177-phosphorylated eNOS in cardiac myocytes." (PMID 32455061, 2020). "For example, netrin-1 overexpression has been shown to suppress IL-6 and COX-2 expression, reduce Th1/Th2/Th17 cytokines from CD4+ T cells, and improve outcomes in models of kidney and cardiac ischemia." (PMID 40728980, 2025). "For example, it is possible that patients experiencing myocardial ischemia and reperfusion injury could be treated with recombinant netrin-1 to activate the HIF1A-netrin-1 pathway for cardioprotection." (PMID 36247475, 2022).
pancreatic ductal adenocarcinoma (6 papers, 2016 to 2025). An infiltrating adenocarcinoma that arises from the epithelial cells of the pancreas. "In a liver metastasis model of PDAC (pancreatic ductal adenocarcinoma), treatment with a NTN1-neutralizing antibody or tumoral knockdown of Neo1 reduced ZEB1 and SOX9 and decreased tumor progression." (PMID 40777309, 2025). "Overexpression of netrin-1 has been shown to impede the growth of pancreatic ductal adenocarcinoma cells by downregulating ITGB4 expression." (PMID 39169946, 2024). "Netrin-1, a guidance cue molecule, exhibits anti-tumorigenic properties in pancreatic ductal adenocarcinoma." (PMID 39169946, 2024). "Nevertheless, there were also opposite opinions that netrin-1 expression was decreased in stage I/II pancreatic ductal adenocarcinoma (PDAC), prostate tumors and nearly half of brain tumors." (PMID 35974411, 2022). "In tumor research, Netrin-1 inhibits the ERK signaling pathway by combining with UNC5B in pancreatic ductal adenocarcinoma, indicating that the pathway is closely related to the mediation of Netrin-1." (PMID 29321724, 2017). "We show that netrin-1 is significantly under-expressed in stage-I/II pancreatic ductal adenocarcinoma (PDAC)." (PMID 27034160, 2016).
peritonitis (6 papers, 2012 to 2025). Inflammation of the peritoneum (tissue that lines the abdominal wall and covers most of the organs in the abdomen). "The endogenous ligand of UNC5B, the NGP netrin-1 has shown potent anti-inflammatory properties in animal models of hypoxia, ventilator associated lung injury, peritonitis and renal ischemia-reperfusion injury." (PMID 23936025, 2013). "Anti-inflammatory actions of netrin-1 were reported as inhibition of migration of leukocytes and protection from vascular inflammation, peritonitis, and pancreatitis through UNC5B receptor." (PMID 30532735, 2018). "The NGP netrin-1, as endogenous ligand of UNC5B, has shown potent anti-inflammatory properties in animal models of hypoxia, ventilator associated lung injury, peritonitis and renal ischemia-reperfusion injury." (PMID 22848430, 2012). "Moreover, in acute peritonitis and acute colitis models, NTN-1 inhibits the migration of inflammatory cells and induces the M2 polarization phenotype of macrophages." (PMID 35095412, 2021).
adenoma (5 papers, 2005 to 2023). A neoplasm arising from the epithelium. "NTN1 overexpression in mouse colons inhibits intestinal epithelial cell apoptosis, inducing colonic hyperplasia and adenoma, and demonstrates an upward trend." (PMID 37674118, 2023). "This inhibition of cell death, in agreement with the model proposed for cell lifespan regulated by netrin-1 control of DCC-induced cell death, is associated with the formation of numerous focal hyperplasias (compared to control mice) and of adenomas." (PMID 15956977, 2005). "Furthermore, overexpression of netrin-1 by cells in the intestinal epithelium of mice led to the formation of focal hyperplasias and adenomas." (PMID 21980448, 2011). "Interestingly, while APC mutated mice develop low-grade adenomas, the development of tumours in the APC/netrin-1 mice was pushed towards high-grade adenoma and adenocarcinoma." (PMID 15956977, 2005).
amyloid (5 papers, 2021 to 2024). "Moreover, an evaluation of the diagnostic value of netrin-1 as combined with amyloid pathology/neurodegeneration blood biomarkers (e.g., Aβ, Tau and phosphorylated Tau) and amyloid-PET findings would provide further pertinent information regarding their use and validity as AD markers." (PMID 35250531, 2021).
brain tumor (5 papers, 2011 to 2022). "Therefore, the aim of our study was to investigate netrin-1 expression in a large cohort of brain metastasis and to analyze its suitability as a prognostic marker serving as a basic rationale for future anti-netrin-1 treatment approaches in secondary brain tumors." (PMID 24647424, 2014).
chronic kidney disease (5 papers, 2011 to 2025). Impairment of the renal function secondary to chronic kidney damage persisting for three or more months. "Our aim was to determine the influence of netrin-1 on renal EndoMT in chronic kidney disease by studying its effect in 5/6 nephrectomized (Nx) rats." (PMID 27176224, 2016). "Studies performed in acute and chronic kidney disease as well as disease of other organs have clearly indicated that netrin-1 is a useful therapeutic agent to control inflammation and tissue injury acting at multiple levels." (PMID 24991088, 2014). "This review will focus on recent advances in understanding netrin-1 mediated regulation of inflammation during acute and chronic kidney disease and whether netrin-1 and its receptor activation can be used to treat acute and chronic kidney disease." (PMID 24991088, 2014).
coloboma (5 papers, 2019 to 2025). An abnormality in which a part of a structure in one or both eyes is missing. "Targeted loss of Netrin-1 results in highly penetrant colobomas in mice and zebrafish, with mouse embryos displaying additional fusion defects in the developing inner-ear and palate." (PMID 33505973, 2020). "Therefore, we propose that NTN1 should be included as a candidate gene in diagnostic sequencing of patients with human ocular coloboma, and should also be carefully considered for those with other congenital malformations involving defective fusion." (PMID 31162046, 2019). "Our cross-species meta-analysis also provided evidence that genes previously associated with coloboma causation in model organisms, such as VAX1, NTN1, and NID1, should be more widely recognised as possible human MAC candidates." (PMID 36830662, 2023). "We observe that our Ntn1 cKO also exhibit colobomas (80% penetrance, n = 5), suggesting that Netrin-1 at the optic disc is required for proper choroid fissure closure." (PMID 32096760, 2020). "It was recently shown that Netrin-1 is required for choroid fissure closure, and that Ntn1-/- mice display highly penetrant colobomas." (PMID 32096760, 2020). "Our data suggest that NTN1 is a strong candidate locus for human coloboma and other multi-system developmental fusion defects, and show that chick OFC is a powerful model for epithelial fusion research." (PMID 31162046, 2019). "We propose that NTN1 should therefore now be considered as a new candidate for ocular coloboma and congenital malformations that feature defective epithelial tissue fusion." (PMID 31162046, 2019). "It is also consistent with our observations in Netrin-1 knock-out animals having a high penetrance of both coloboma and cleft palate phenotypes." (PMID 31162046, 2019). "(f) Ntn1-/- mice exhibited highly penetrant (~90%) bilateral coloboma (arrows; n = 10/11 homozygous E15.5-E16.5 animals analysed)." (PMID 31162046, 2019). "Among these were the known human MAC genes TENM3, SMOC1, PAX2, ALDH1A3, and BMPR1B, in addition to NID1, VAX1, and NTN1, which have been previously identified as MAC or coloboma candidates based on animal studies." (PMID 36830662, 2023). "The functional mechanisms of NTN1 in fusion are is currently unclear, but these transcriptional approaches revealed NTN1 as a novel OCF/coloboma gene among many other plausible candidates." (PMID 33505973, 2020). "We applied this resource to a pertinent developmental context - coloboma is a structural eye malformation characterised by failure of epithelial fusion during optic fissure closure (OFC) and NTN1 is specifically expressed in fusion pioneer cells at the edges of the optic fissure." (PMID 40128351, 2025). "In mice completely lacking Ntn1 the fissure margins were normally decorated in Laminin and came into direct contact, but fusion did not initiate and led to highly penetrant colobomas." (PMID 33505973, 2020).